RPS3A (ribosomal protein S3A)
Description:
Component of the small ribosomal subunit. The ribosome is a large ribonucleoprotein complex responsible for the synthesis of proteins in the cell. Part of the small subunit (SSU) processome, first precursor of the small eukaryotic ribosomal subunit. During the assembly of the SSU processome in the nucleolus, many ribosome biogenesis factors, an RNA chaperone and ribosomal proteins associate with the nascent pre-rRNA and work in concert to generate RNA folding, modifications, rearrangements and cleavage as well as targeted degradation of pre-ribosomal RNA by the RNA exosome. May play a role during erythropoiesis through regulation of transcription factor DDIT3 (By similarity).
Synonyms: FTE1; MFTL; S3A; eS1
Tractability: Small molecule: an approved drug acts on it; a structure with a bound ligand is known; a high-quality ligand is known. PROTAC: UniProt records ubiquitination sites on it; ubiquitination databases record sites on it; its protein half-life has been measured; a small molecule that binds it is known. Other modalities: a drug acting on it is in phase 2 or 3 trials.
Target class: Other cytosolic protein
Gene: Protein-coding gene on chromosome 4 (151,099,565 to 151,104,652, forward strand). Ensembl gene ENSG00000145425.
Subcellular location: Cytoplasm; Nucleus; Nucleus, nucleolus
Subcellular location (Human Protein Atlas): Cytosol; Endoplasmic reticulum; Nucleoli
Pathways (Reactome):
Metabolism of proteins: Eukaryotic Translation Termination; Formation of a pool of free 40S subunits; Formation of the ternary complex, and subsequently, the 43S complex; GTP hydrolysis and joining of the 60S ribosomal subunit; L13a-mediated translational silencing of Ceruloplasmin expression; PELO:HBS1L and ABCE1 dissociate a ribosome on a non-stop mRNA; Peptide chain elongation; Ribosomal scanning and start codon recognition; SRP-dependent cotranslational protein targeting to membrane; Translation initiation complex formation; ZNF598 and the Ribosome-associated Quality Trigger (RQT) complex dissociate a ribosome stalled on a no-go mRNA
Disease: SARS-CoV-1 modulates host translation machinery; SARS-CoV-2 modulates host translation machinery; Viral mRNA Translation
Metabolism of RNA: Major pathway of rRNA processing in the nucleolus and cytosol; Nonsense Mediated Decay (NMD) enhanced by the Exon Junction Complex (EJC); Nonsense Mediated Decay (NMD) independent of the Exon Junction Complex (EJC)
Cellular responses to stimuli: Response of EIF2AK4 (GCN2) to amino acid deficiency
Developmental Biology: Regulation of expression of SLITs and ROBOs
Metabolism: Selenocysteine synthesis
Gene Ontology:
Molecular function: mRNA 5'-UTR binding; protein binding; RNA binding; structural constituent of ribosome
Biological process: negative regulation of apoptotic process; ribosomal small subunit biogenesis; translation; cytoplasmic translation; translational initiation
Cellular component: cytoplasm; cytosol; cytosolic ribosome; cytosolic small ribosomal subunit; endoplasmic reticulum; extracellular exosome; focal adhesion; nucleolus; nucleus; ribonucleoprotein complex; small-subunit processome; nucleoplasm; ribosome; synapse
Genetic constraint (gnomAD): Loss-of-function variants: 1 observed, 16.33 expected, observed/expected ratio (o/e) 0.0613, 90% interval 0.021 to 0.29. The upper end of that interval is the gene's LOEUF score, 0.29, which puts it in group 1 of 6, group 1 being the genes least tolerant of losing a copy. Missense variants: 108 observed, 221.26 expected, observed/expected ratio (o/e) 0.49, 90% interval 0.42 to 0.57. Synonymous variants: 76 observed, 67.71 expected, observed/expected ratio (o/e) 1.12, 90% interval 0.93 to 1.36.
Homologues: Orthologues: chimpanzee RPS3A (100% identical), dog RPS3A (100% identical), guinea pig RPS3A (100% identical), pig RPS3A (100% identical), rabbit RPS3A (100% identical), zebrafish rps3a (94% identical), tropical clawed frog rps3a (92% identical), Drosophila melanogaster RpS3A (69% identical), Caenorhabditis elegans rps-1 (63% identical).
Diseases named in the same sentence as RPS3A in open-access papers:
RPS3A is named in the same sentence as 41 diseases in open-access papers, as found by Europe PMC text mining. Sharing a sentence is not in itself a finding about the gene and the disease. The quoted sentences say what the papers report.
hepatocellular carcinoma (7 papers, 2011 to 2024). A malignant tumor that arises from hepatocytes. "High RPS3A expression levels were strongly associated with low tumor immune cell infiltration levels and an unfavorable prognosis in hepatocellular carcinoma patients." (PMID 40453362, 2024). "When overexpressed in hepatocellular carcinoma cells, RPS3A was recently found to exert an extraribosomal chaperoning activity on HBx, preventing its aggregation into inclusions." (PMID 23924367, 2013). "Most of the over-expressed ribosomal proteins activated the HBx-induced NF-κB signal; among them, RPS3a hyperactivated the HBx transactivity in the hepatoma cell line." (PMID 21857917, 2011). "RPS3a is highly expressed in most tumors, such as hepatocellular carcinoma and other cancers." (PMID 35928229, 2022). "In addition, RPS3a is highly expressed in most tumors including hepatocellular carcinoma and other cancers." (PMID 21857917, 2011).
atherosclerosis (3 papers, 2018 to 2025). A disease characterized by the build-up of fatty material and calcium deposition in the arterial wall resulting in partial or complete occlusion of the arterial lumen. "Indeed, reducing RPS3A in periaortic adiposetissue in an atherosclerosis mouse model impaired the browning process inperivascular adipose tissue, leading to increased vascular inflammation andaccelerated atherosclerosis development." (PMID 40160564, 2025). "One study from Tang laboratory have revealed that periaortic knockdown of ribosomal protein S3A (RPS3A) in mouse PVAT impaired PVAT browning, promoted vascular inflammation and atherosclerosis development by modulating UCP-1 expression in ApoE-/- mice." (PMID 36172381, 2022). "Importantly, ApoE−/− atherosclerosis mice had decreased expression of UCP1, PGC1α, PRDM16, Cidea, and RPS3A." (PMID 30131868, 2018). "Moreover, RPS3A knockdown in mouse periaortic adipose tissue impaired browning of PVAT, accelerated vascular inflammation, and atherosclerosis progression." (PMID 30131868, 2018).
Alzheimer disease (2 papers, 2013 to 2024). A progressive, neurodegenerative disease characterized by loss of function and death of nerve cells in several areas of the brain leading to loss of cognitive function such as memory and language. "One genetic linkage study claimed that a mutation in RPS3A, SNP rs498055, is linked to late-onset Alzheimer's disease; however, that conclusion was later contradicted by three other studies." (PMID 23924367, 2013). "Additional literature implicates RPS3A expression upregulation in Alzheimer’s disease and poor prognosis in HCC." (PMID 38732249, 2024). "Notably, six of these proteins (RPS3A, RPS4X, RPS8, RPS14, RPS20 and RPL31) were upregulated in brain capillaries of Alzheimer’s disease patients." (PMID 38732249, 2024).
coronary artery diseases (2 papers, 2018 to 2023). "Moreover, RPS3A positively regulated the mitochondrial function of human periaortic adipose tissues and was associated with the risk of coronary artery diseases." (PMID 37274336, 2023).
lung carcinoma (2 papers, 2011 to 2021). "RPS3a has been reported to be highly expressed in most tumors including HCC, thyroid carcinoma, virus-associated lymphoma, lung cancer, colorectal cancer and thymic tumor." (PMID 21857917, 2011).
adenoma (1 paper, 2025). A neoplasm arising from the epithelium. "While nominally significant, the expression of RPS3A was elevated in CIS compared to adenoma and adenocarcinoma." (PMID 40362431, 2025). "In addition, while not ranked as well in the top 20 frequently occurring genes, RPS3A (p = 0.048) was a putative biomarker that may distinguish CIS from adenoma." (PMID 40362431, 2025). "In adenoma, ARRB1, CTBP1 and CTBP2 were overexpressed, suggesting their involvement in early tumorigenesis, whereas in CIS, RPS3A and COL4A5 were overexpressed, suggesting their involvement in the transition from benign to malignant stage." (PMID 40362431, 2025). "Among the identified molecular targets, ARRB1 was validated using RT-qPCR for adenoma, COL4A5 and RPS3A for CIS, and COL1A2 and MED10 for adenocarcinoma." (PMID 40362431, 2025).
alcohol addiction (1 paper, 2023). "However, four genes, SERPINA3, SLC14A1, RPS6 and RPS3A, were obtained among the alcohol addiction-related differential genes." (PMID 37065902, 2023).
coronary atherosclerosis (1 paper, 2023). Atherosclerosis of the coronary vasculature. "Moreover, RPS3A, BCL6, and S100B play a critical role in coronary atherosclerosis." (PMID 37316908, 2023).
COVID-19 (1 paper, 2022). A disease caused by infection with severe acute respiratory syndrome coronavirus 2. "Among the classification rules for indicating COVID-19, the expression level of RPS3A in CD8+ T cells was involved in several criteria based on single-cell multi-omics data." (PMID 35928229, 2022). "Our analysis results may imply a potential functional role of RPS3A in COVID-19." (PMID 35928229, 2022). "No reports directly related to RPS3A and COVID-19 were found." (PMID 35928229, 2022).
diabetic nephropathy (1 paper, 2023). "Interestingly, RPS3 was described to be associated with diabetic nephropathy, while RPS3A was also reported to have an increased expression in membranous nephropathic kidneys." (PMID 36769128, 2023).
ovarian carcinoma (1 paper, 2023). A malignant neoplasm originating from the surface ovarian epithelium. "It has the potential as a molecular marker of ovarian cancer; Ribosomal Protein S3A (RPS3A) is a member of the S3AE family of ribosomal proteins, and also a component of the 40S subunit." (PMID 37065902, 2023).
prostate adenocarcinoma (1 paper, 2025). "Overexpression of RPS3A induces tumor formation by suppressing apoptosis, and its expression is markedly elevated in prostate adenocarcinoma." (PMID 41468516, 2025).
schizophrenia (1 paper, 2018). A major psychotic disorder characterized by abnormalities in the perception or expression of reality. "The SLC25A5, NONO, LMNA and RPS3A proteins were not chosen for validation because little information about the relation between schizophrenia and these proteins is available." (PMID 29514709, 2018).
tumor (13 papers, 2009 to 2026). "The representative immunohistochemistry data show that the endogenous level of RPS3a protein is significantly higher in the tumor regions of HBV-associated HCC than in non-tumor regions." (PMID 21857917, 2011). "To date, a number of studies have shown that RPS3a is associated with cell proliferation, differentiation and tumor formation." (PMID 21857917, 2011). "Consistent with the previous results, the RPS3a expression is significantly higher in tumor regions of HBV-associated HCC tissues than in peripheral non-tumor regions." (PMID 21857917, 2011). "The high recurrence of genes like C1QBP and RPS3A in Luminal A, USP31 and RRM1 in Luminal B, and PSMD8 and YME1L1 in Basal subtypes highlights the subtype-specific regulatory networks that underlie tumor progression." (PMID 39596229, 2024). "High expression of RPS3A correlated with low tumor immune cell infiltration and an unfavorable prognosis in patients with HCC." (PMID 37274336, 2023). "Immunohistochemical analysis of 20 cases of HBV-positive HCC tissues, paring non-tumor and tumor tissues was carried out using anti-RPS3a antibody." (PMID 21857917, 2011). "And we showed that protein level of RPS3a is significantly higher in the HBV-related HCC tissues as compared with non-tumor tissues." (PMID 21857917, 2011). "Immunoprecipitation experiments confirmed that RPS3A and C/EBPβ interacted within tumor cells." (PMID 40470795, 2025). "In addition, the knockdown of Myh9, Cyb5r3, or RPS3A inhibited tumorigenicity and tumor growth in a subcutaneous xenograft tumor model under HFD conditions." (PMID 40470795, 2025). "In addition, RPS3A knockdown inhibited the accumulation of LDs in tumor cells." (PMID 40470795, 2025). "Overexpression of both BTN3A3 and RPS3A increases cellular oxygen consumption rate (OCR) and reactive oxygen species (ROS) levels, which play a role in regulating the Mitogen-activated protein kinases (MAPKs) pathway and tumor cell growth." (PMID 39891297, 2025). "Single sample gene set enrichment analysis (ssGSEA) and immunohistochemistry also exhibited a strong negative correlation between ribosomal protein S3a (RPS3A) expression and the infiltration of tumor immune cell." (PMID 39487553, 2024). "The 70% (14 cases) of HBV-positive HCC tissues showed considerably over-expression of RPS3a in tumor regions compared with the corresponding peripheral non-tumor regions." (PMID 21857917, 2011). "First, we compared the relative mRNA levels of RPS3a between tumor and non-tumor regions in the tissues from three HBV-associated HCC patients (IBR approved), using semi-quantitative reverse transcription PCR." (PMID 21857917, 2011). "In addition, RPS3A also interacts with HBx protein through N-terminal domain to enhance the expression of intracellular soluble HBx protein, which then activates HBX-induced NF-κB signaling pathway and enhances the possibility of HBV-induced tumor development." (PMID 39487553, 2024).
cancer (5 papers, 2010 to 2024). A tumor composed of atypical neoplastic, often pleomorphic cells that invade other tissues. "RPS3A is a component of the ribosomal machinery, and its overexpression is associated with increased protein synthesis, a hallmark of rapidly dividing cancer cells." (PMID 39596229, 2024). "Interestingly, RPS3a has been associated with cell transformation, growth and many cancers." (PMID 21857917, 2011). "In this regard, RPS3a might be another class of molecular chaperone acting on cancer-related proteins including cellular and viral proteins." (PMID 21857917, 2011). "Some other genes differentially expressed in this pool of cells CD133+ and also involved in cancer and neurological disease are RPS4X, RPS3A or TUBA1B." (PMID 20735813, 2010). "However, the biochemical roles of RPS3a in these cancers have not been known yet." (PMID 21857917, 2011).
infection (4 papers, 2018 to 2026). The state of being infected such as from the introduction of a foreign agent such as serum, vaccine, antigenic substance or organism. "This allele is expressed during infection but differs by two amino acids from Avr3a45C (K64P and A65S), a change that could possibly explain the differential responses of Rps3a and Rps8 towards its gene product." (PMID 35150190, 2022). "Consistent with these molecular profiles, virulence assays on soybean plants carrying Rps1b or Rps3a revealed differential restoration of infection ability." (PMID 41505097, 2026). "In Phytophthora sojae the avirulence factor Avr3a is silenced by sRNAs, leading to infection of plants carrying the R-gene Rps3a." (PMID 31345162, 2019).
neurodegenerative disease (1 paper, 2020). A disorder of the central nervous system characterized by gradual and progressive loss of neural tissue and neurologic function. "When nerve cells become aged, the protective effect of RPS3A might be reduced, which results in α-synaptic nucleoprotein becoming increasingly toxic and leads to the eventual progression of neurodegenerative diseases." (PMID 32308643, 2020).
RPS3A also shares sentences with these, for which no sentence is quoted: adenocarcinoma (1 paper); autism spectrum disorder (1); autoimmune disease (1); bacterial infection (1); Brachycephaly (1); breast carcinoma (1); Cirrhosis (1); clear cell renal cell carcinoma (1); coenzyme Q10 deficiency (1); colorectal cancer (1); developmental delay (1); Diamond-Blackfan anemia (1); endometrial carcinoma (1); epilepsy (1); IgA nephropathy (1); inflammation (1); liver cirrhosis (1); neurological disease (1); psoriasis (1); systemic lupus erythematosus (1); thymic tumor (1); thyroid carcinoma (1); trichomegaly (1); type 1 diabetes (1).